Y_RNA (Y RNA )
Gene: Miscellaneous RNA gene on chromosome 6 (151,378,000 to 151,378,099, reverse strand). Ensembl gene ENSG00000252615.
Homologues: Orthologues: chimpanzee Y_RNA (95% identical). Paralogues in human: RNY1 (83% identical), Y_RNA (83% identical), Y_RNA (82% identical), RNY1P11 (81% identical), Y_RNA (81% identical), Y_RNA (80% identical), RNY1P12 (79% identical), Y_RNA (79% identical), RNY1P15 (78% identical), RNY1P8 (78% identical), Y_RNA (78% identical), RNY1P10 (77% identical), and 93 more.